RBM8A (RNA binding motif protein 8A)
Diseases named in the same sentence as RBM8A in open-access papers (continued):
Sharing a sentence is not in itself a finding about the gene and the disease.
thrombocytopenia-absent radius syndrome (5 papers, 2019 to 2026). Thrombocytopenia-absent radius (TAR) syndrome is a very rare congenital malformation syndrome characterized by bilateral radial aplasia and thrombocytopenia. "The C-terminus of the Y14 protein, which is also known as RBM8A and is encoded by the gene responsible for human thrombocytopenia absent radius syndrome, contains two serines that undergo phosphorylation inside an intrinsically disordered region (IDR)." (PMID 41972736, 2026). "Thrombocytopenia absent radii (TAR) syndrome results from a combination of a microdeletion on Chromosome 1 including the RBM8A gene alongside a low frequency non-coding single nucleotide polymorphism (SNP) within the regulatory region of RBM8A." (PMID 31275945, 2019).
autism (4 papers, 2015 to 2024). Persistent deficits in social interaction and communication and interaction as well as a markedly restricted repertoire of activity and interest as well as repetitive patterns of behavior. "In addition, RBM8A is located in the 1q21 region of the genome, which is associated with neurodevelopmental disorders, such as autism and SZ38,39." (PMID 33154347, 2020). "Interestingly, autism and schizophrenia risk genes are highly represented in downstream transcripts of RBM8a." (PMID 26094033, 2015). "Demonstrating the opposite, pre-clinical studies of a nonsense-mediated decay regulatory gene associated with autism, Rbm8a, showed abnormally increased mEPSCs, pointing to alterations in LTD being associated with autism." (PMID 38352654, 2024).
cervical carcinoma (4 papers, 2020 to 2022). A carcinoma arising from either the exocervical squamous epithelium or the endocervical glandular epithelium. "High expression of RBM8A can also down-regulate splicing variants of multiple pro-apoptotic genes, such as Bcl-X, which inhibits apoptosis of prostate and cervical cancer cells." (PMID 34804926, 2021). "Knockdown studies of RBM8A in human cervical carcinoma cell line (HeLa) and human lung adenocarcinoma cell line (A549) further established the role of RBM8A in cell cycle regulation." (PMID 36142288, 2022). "RBM8A is known to be a component of the exon junction complex, which could regulate IL-6-induced STAT3 activation in human cervix carcinoma cell line." (PMID 32294703, 2020).
lung adenocarcinoma (4 papers, 2021 to 2022). A carcinoma that arises from the lung and is characterized by the presence of malignant glandular epithelial cells. "Knocking down RBM8A in lung adenocarcinoma cells arrested the cell cycle, inhibited cell proliferation, activated caspases 3 and 7, and increased the proportion of apoptotic cells containing abnormal centrosomes." (PMID 34804926, 2021). "Cell growth was blocked in RBM8A knockout cells, and the G2/M step of the cell cycle was arrested in lung adenocarcinoma cells." (PMID 33692831, 2021).
MRKH syndrome (4 papers, 2018 to 2022). "More accurately, variants of the RBM8A gene—which is located in this chromosomal region—have been proposed as the possible cause of MRKH syndrome and gonadal dysgenesis, as this gene mainly affects oocyte differentiation and determination of the primordial germ cells." (PMID 35883945, 2022). "In cases of MRKH syndrome, recurrent microdeletions and microduplications (1q21,1; 2q12.1q14.1; 16p11.2; 17p14.3; 17q12; 22q11.21; 22q11.21q11.23) and mutations in genes located on these loci (RBM8A, PAX8, TBX1, TBX6, LHX, HNF1B, WNT4) have been identified." (PMID 33883018, 2021). "Furthermore, in a patient with MRKH I and XX gonadal dysgenesis, a heterozygous RBM8A missense mutation was found, making RBM8A an interesting candidate for MRKH syndrome associated with ovarian dysgenesis too." (PMID 29527097, 2018). "By analysing candidate genes, being located in these aberrations, mutations in genes such as LHX1, RBM8A and TBX6 have been identified as being causative of MRKH syndrome." (PMID 29527097, 2018). "For example, 1q21 deletion (involving RBM8A gene), identified in a 46,XX patient, is a described etiology in Mayer-Rokitansky-Küster-Hauser syndrome, which is present in some patients with this BP2-BP3 deletion." (PMID 34829455, 2021).
Anxiety (3 papers, 2020 to 2022). Intense feelings of nervousness, tension, or panic often arise in response to interpersonal stresses. "In an animal study, over-expression of RBM8a in the dentate gyrus of the hippocampus of mice induced abnormal behaviors, in anxiety and depression models such as open field test, social interaction test, and forced swimming test." (PMID 35509884, 2022). "Moreover, RBM8A plays a key role in adult neurogenesis and in regulating anxiety-related behavior, further supporting the important role of RBM8A in psychiatric diseases." (PMID 34071723, 2021).
liver cancer (3 papers, 2021 to 2022). An epithelial or non-epithelial malignant neoplasm that arises from the liver. "In liver cancer tissues, elevated expression of RBM8A promotes cell proliferation, inhibits apoptosis, and induces the epithelial-mesenchymal transition of tumor cells; higher expression also correlates with worse prognosis." (PMID 34804926, 2021).
lymph node metastasis (3 papers, 2020 to 2022). "In multivariate analysis, both increased RBM8A expression (HR=0.470, 95%CI=0.322−0.871; P<0.0018) and lymph node metastasis (HR=3.271, 95%CI=2.873−4.002; P<0.001) induced worse prognosis independently." (PMID 32294703, 2020). "The protein level of RBM8A was correlated with tumor size (P=0.031), depth of invasion (P<0.001), lymph node metastasis (P<0.001), TNM stage (<0.001), and distant metastasis (P=0.001)." (PMID 32294703, 2020). "Our results illustrated that the high and low expression of RBM8A showed significant differences in TNM stage (P < 0.01) and lymph node metastasis (LNM) (P < 0.05)." (PMID 36105365, 2022). "Patients with increased RBM8A expression (P<0.0018, 95%CI=0.322−0.871), higher TNM stage (P<0.001, 95%CI=4.990−11.283), and lymph node metastasis (P<0.001, 95%CI=2.873−4.002) had a lower overall survival." (PMID 32294703, 2020).
mesothelioma (3 papers, 2021 to 2023). A usually malignant and aggressive neoplasm of the mesothelium which is often associated with exposure to asbestos. "In the exons, 3'UTR is the most edited region consistent with previous observations and we have recently shown that editing of the 3'UTR of RBM8A in mesothelioma cells increases protein levels by counteracting the negative regulation by Musashi2." (PMID 36221913, 2022). "In this study, we show that RBM8A protein levels are higher in mesothelioma cells compared to normal mesothelial cells." (PMID 34944051, 2021). "The aim of this study was to further characterize the role of RBM8A in mesothelioma and the consequences of its mRNA editing." (PMID 34944051, 2021). "The silencing of MSI2 in mesothelioma or overexpression of Adar2 in mesothelial cells resulted in increased RBM8A protein levels." (PMID 34944051, 2021). "In normal mesothelial cells, only 25% of the overall RBM8A expression corresponds to the RBM8A-204 transcript, which is similar to its abundance observed in tumors, including mesothelioma, and human tissues in general, although heterogeneity was observed." (PMID 34944051, 2021). "RBM8A protein is heterogeneously expressed in mesothelioma cell lines, and the average levels are 4-fold higher in mesothelioma cell lines (n = 14) when compared to normal mesothelial cells (n = 5) (p < 0.05)." (PMID 34944051, 2021). "Silencing RBM8A changed splicing patterns in mesothelial and mesothelioma cells but drastically reduced viability only in mesothelioma cells." (PMID 34944051, 2021). "Therefore, ADAR-dependent editing contributes to maintaining elevated RBM8A protein levels in mesothelioma by counteracting MSI2-driven downregulation." (PMID 34944051, 2021). "We analyzed RBM8A protein expression in several mesothelioma cell lines." (PMID 34944051, 2021). "In addition, we demonstrate that higher protein levels of RBM8A in mesothelioma are due to increased RNA editing of its 3′UTR, which protects it from MSI2 binding and negative translational regulation." (PMID 34944051, 2021). "Indeed, miR-29a downregulates Rbm8a in retinal progenitors, and miR-29 levels are lower in mesothelioma cells compared to mesothelial cells." (PMID 34944051, 2021). "This is consistent with the knowledge that increased levels of mRNA-binding proteins such as RBM8A are a hallmark of cancer; accordingly, silencing RBM8A drastically reduces cell growth in mesothelioma but not in mesothelial cells." (PMID 34944051, 2021). "RBM8A protein expression was higher in mesothelioma compared to mesothelial cells." (PMID 34944051, 2021). "While no significant increase in Rbm8a mRNA expression was detected in asbestos-exposed mesothelium, we observed increased nuclear Rbm8a immunoreactivity in mesothelial cells and mesothelioma tumors upon asbestos exposure, indicating that RNA editing coincided with increased protein levels." (PMID 34944051, 2021). "In addition, although editing of RBM8A was investigated in mesothelioma in this study, it is likely to occur in other cancer types as well." (PMID 34944051, 2021). "However, the RBM8A-204 transcript is selectively enriched in the human mesothelioma translatome compared to normal mesothelium, indicating that the length of the 3′UTR might be important for the translational regulation of RBM8A." (PMID 34944051, 2021).
non-small cell lung carcinoma (3 papers, 2021). A group of at least three distinct histological types of lung cancer, including non-small cell squamous cell carcinoma, adenocarcinoma, and large cell carcinoma. "Similarly, silencing RBM8A killed non-small-cell lung cancer (NSCLC) cells and not nonmalignant lung cells, suggesting that RBM8A could be a cancer-selective target." (PMID 34944051, 2021).
schizophrenia (3 papers, 2015 to 2023). A major psychotic disorder characterized by abnormalities in the perception or expression of reality. "In particular, a core exon junction complex (EJC) factor, RBM8a (located in the 1q21.1 chromosome region) is associated with ID, ASD, schizophrenia (SCZ), and microcephaly." (PMID 26094033, 2015). "In addition to cancer, abnormal expression of RBM8A plays a role in thrombocytopenia and neurodevelopmental diseases, such as autism and schizophrenia." (PMID 36142288, 2022). "Thus, abnormal expression of RBM8A has been studied in neurodegenerative, neurodevelopmental, and neuropsychiatric research regarding Alzheimer’s disease, autism spectrum disorder, and schizophrenia." (PMID 36142288, 2022).
glioma (2 papers, 2021). A benign or malignant brain and spinal cord tumor that arises from glial cells (astrocytes, oligodendrocytes, ependymal cells). "Using in vitro and in vivo assays, combined with GBM sequencing data from the Cancer Genome Atlas (TCGA) and the Chinese Glioma Genome Atlas (CGGA), we examined whether and how RBM8A contributes to GBM progression." (PMID 34804926, 2021).
prostate carcinoma (2 papers, 2021). A carcinoma that arises from epithelial cells of the prostate gland.
rectum adenocarcinoma (2 papers, 2021 to 2022). An adenocarcinoma arising from the rectum. "In contrast, for only rectum adenocarcinoma, QKI and RBM8A were recognized as such." (PMID 35885025, 2022).
Alzheimer disease (1 paper, 2019). A progressive, neurodegenerative disease characterized by loss of function and death of nerve cells in several areas of the brain leading to loss of cognitive function such as memory and language. "The present study aimed to explore the role of RBM8A in Alzheimer's disease (AD)." (PMID 31816601, 2019). "For example, RBM8A is an RNA binding protein that has differential expression in Alzheimer's disease, and DNA methylation on RHBDF 2 gene may have a role in the onset of AD, the increase of CBLN4 may be a potential therapy for AD." (PMID 31816601, 2019).
autism spectrum disorder (1 paper, 2023). A spectrum of developmental disorders that includes autism, and Asperger syndrome. "Additionally, de novo mutations in RBM8A have been associated with autism spectrum disorders (ASD) and the Mayer–Rokitansky–Küster–Hauser (MRKH) syndrome (MIM 277000)." (PMID 36902031, 2023).
DiGeorge syndrome (1 paper, 2016). "Various promising CNVs have been reported located at 1q21.1 (RBM8A), 16p11.2 (TBX6), 17q12 (LHX1, HNF1B), as well as 22q11 associated with DiGeorge syndrome." (PMID 28003020, 2016).
fungal infection (1 paper, 2014). "For example, dps-miR-210b was downregulated by fungal infection, and targeted mRNAs encoding RNA-binding motif protein 8a, transmembrane protein 201, 1-acylglycerol-3-phosphate acyltransferase and quiescin sulfhydryl oxidase." (PMID 25149864, 2014).
kidney chromophobe (1 paper, 2021). "Lower expression of RBM8A was observed in kidney chromophobe (KICH), kidney renal papillary cell carcinoma (KIRP), kidney renal clear cell carcinoma (KIRC), and thyroid carcinoma (THCA)." (PMID 34326876, 2021).
neuroblastoma (1 paper, 2015). Neuroblastoma (NB) is the most common solid, extracranial childhood tumor. "The two shRNAs specifically knocked down RBM8a in CAD cells, a well-established mouse neuroblastoma cell line, which can proliferate and differentiate." (PMID 26094033, 2015).
osteoporosis (1 paper, 2025). A condition of reduced bone mass, with decreased cortical thickness and a decrease in the number and size of the trabeculae of cancellous bone (but normal chemical composition), resulting in increased fracture incidence. "The RBM8A mRNA did not change in the alveolar bone of postmenopausal women with (P11‐P20) or without osteoporosis (P1–P10) according to RT‐qPCR analysis." (PMID 40051055, 2025).
psoriasis (1 paper, 2015). An autoimmune condition characterized by red, well-delineated plaques with silvery scales that are usually on the extensor surfaces and scalp. "Similarly, we identified DEG-encoded uDBPs that interact with PREs, whose function in psoriasis is presently unknown (e.g., AVEN, RBM8A, GPAM, WISP2)." (PMID 25883770, 2015). "This highlighted SNP-PRE pairs involving PREs recognized by TFs or uDBPs with increased expression in psoriasis lesions (i.e., AVEN, RBM8A and FOXM1)." (PMID 25883770, 2015). "Through in silico screening of known DNA binding sites, our findings highlight proteins not yet well studied in psoriasis, including TFs (FOXM1, EHF, SOX5) and uDBPs (AVEN, RBM8A, GPAM, WISP2)." (PMID 25883770, 2015).
tumor (18 papers, 2019 to 2024). "RBM8A depletion regulates the expression of pro-apoptotic genes, such as Bcl-Xs and Bim, and tumor development associated with mRNA splicing regulation." (PMID 36142288, 2022). "Similarly, RBM8A expression appears to be linked to complement activation, which can promote tumor growth and metastasis." (PMID 35573726, 2022). "Furthermore, another study found the cell cycle stalling at the G2/M checkpoint in human tumor cells deficient for RBM8A." (PMID 36142288, 2022). "We found that RBM8A may compete with DLEU1 for binding to miR-128-1-5p, and aberrant RBM8A expression was associations with tumor infiltration by immune cells." (PMID 35573726, 2022). "Based on the association observed in our study between RBM8A expression levels and tumor progression, we conclude that RBM8A may function as an independent prognostic factor and therapeutic target in the management of GBM." (PMID 34804926, 2021). "RBM8A depletion in human A549 tumor cells results in apoptosis, supporting the critical role of MAGOH and RBM8A in proper mitotic phase progression, which can serve as a potential anticancer therapeutic target." (PMID 38534343, 2024). "Results also show that RBM8A expression affects tumor diameter, degree of pathological differentiation and clinical stage, overall survival, and progression-free survival." (PMID 36142288, 2022). "As expected, animal experiments showed that RBM8A inhibition retarded the growth of tumor xenograft in mice." (PMID 36105365, 2022). "RBM8A promotes tumor cell migration and invasion in HCC by activating the EMT signaling pathway in vitro." (PMID 36105365, 2022). "RBM8A knockdown inhibits tumor cell activity, arrests the cell cycle at the M phase, and promotes apoptosis." (PMID 36142288, 2022). "We found that tumor tissues of GBM patients expressing high levels of RBM8A show substantial infiltration by B cells and central memory T cells." (PMID 35573726, 2022). "RBM8A differential expression has been noted in several cancers types but observed more expressed in the tumor than in the normal tissue, which seems counterintuitive." (PMID 35406420, 2022). "RBM8A up-regulation is critically involved in modulating apoptosis, and tumor proliferation and metastasis." (PMID 33692831, 2021). "Among the 76 patients with follow-up data, those with low nuclear levels of RBM8A expression in tumor tissues (n = 26) exhibited significantly longer overall survival than those with high nuclear RBM8A expression (n = 50)." (PMID 34804926, 2021). "Tumor growth was much slower in the RBM8A-KD group than in the control group, with average tumor diameter 0.25 ± 0.15 mm3 in RBM8A-KD animals and 11.92 ± 4.98 mm3 in NC animals (p=001; n=5 per group)." (PMID 34804926, 2021). "The results demonstrated that the expression levels of RBM8A displayed strong correlation with the tumor stages in patients with GC (P<0.05)." (PMID 32294703, 2020). "We also used the public TCGA (The Cancer Genome Atlas) database to study the expression level of RBM8A in GC, and analyzed the relationship between its expression and tumor stages, as well as prognosis." (PMID 32294703, 2020). "We analyzed the correlation between RBM8A expression and tumor stage in patients with GC by bioinformatics." (PMID 32294703, 2020). "The expression level of RBM8A protein in GC was significantly correlated with tumor size (P=0.031), depth of invasion (P<0.001), lymph node metastasis (P<0.001), TNM stage (P<0.001), and distant metastasis (P=0.001)." (PMID 32294703, 2020). "Meanwhile, we predicted the potential correlation between RBM8A and tumor stages as well as survival condition in patents with GC based on The Cancer Genome Atlas (TCGA) database." (PMID 32294703, 2020).